CENPI (centromere protein I)
Description:
Component of the CENPA-CAD (nucleosome distal) complex, a complex recruited to centromeres which is involved in assembly of kinetochore proteins, mitotic progression and chromosome segregation. May be involved in incorporation of newly synthesized CENPA into centromeres via its interaction with the CENPA-NAC complex. Required for the localization of CENPF, MAD1L1 and MAD2 (MAD2L1 or MAD2L2) to kinetochores. Involved in the response of gonadal tissues to follicle-stimulating hormone.
Synonyms: CENP-I; FSHPRH1; LRPR1; Mis6
Tractability: PROTAC: UniProt records ubiquitination sites on it; ubiquitination databases record sites on it.
Gene: Protein-coding gene on chromosome X (101,098,167 to 101,166,126, forward strand). Ensembl gene ENSG00000102384.
Subcellular location: Nucleus; Chromosome, centromere
Subcellular location (Human Protein Atlas): Nuclear bodies; Nucleoplasm
Pathways (Reactome):
Cell Cycle: Amplification of signal from unattached kinetochores via a MAD2 inhibitory signal; Deposition of new CENPA-containing nucleosomes at the centromere; EML4 and NUDC in mitotic spindle formation; Mitotic Prometaphase; Resolution of Sister Chromatid Cohesion; Separation of Sister Chromatids
Signal Transduction: RHO GTPases Activate Formins
Gene Ontology:
Molecular function: protein binding
Biological process: CENP-A containing chromatin assembly; chromosome segregation; mitotic sister chromatid segregation; sex differentiation
Cellular component: inner kinetochore; kinetochore; nuclear body; nucleoplasm; cytosol; nucleus; chromosome, centromeric region
Homologues: Orthologues: chimpanzee CENPI (98% identical), macaque CENPI (93% identical), dog CENPI (85% identical), pig CENPI (83% identical), rabbit CENPI (79% identical), rat Cenpi (72% identical), mouse Cenpi (72% identical), tropical clawed frog cenpi (44% identical), zebrafish cenpi (38% identical).
Diseases named in the same sentence as CENPI in open-access papers:
CENPI is named in the same sentence as 25 diseases in open-access papers, as found by Europe PMC text mining. Sharing a sentence is not in itself a finding about the gene and the disease. The quoted sentences say what the papers report.
breast carcinoma (3 papers, 2017 to 2023). "Consistent with this notion, CENPI mRNA levels are significantly elevated in breast cancers with RB1 loss (p<0.0001, Mann-Whitney U test)." (PMID 28977935, 2017). "Taken together, these observations indicate that CENPI overexpression in breast cancer cannot be explained by a proliferation-associated effect." (PMID 28977935, 2017). "To further corroborate the prognostic value of CENPI expression, we evaluated distant metastasis-free survival of the breast cancer patients using the pooled datasets." (PMID 28977935, 2017). "We next used the TCGA breast cancer RNAseq dataset to evaluate CENPI mRNA expression in the four well-established molecular subtypes: luminal A, luminal B, Her2-type and basal-like breast cancers." (PMID 28977935, 2017). "Well-established prognostic tests indicate that CENPI overexpression constitutes a powerful independent marker for poor patient prognosis and survival in ER+ breast cancer." (PMID 28977935, 2017). "The tight correlation between CIN70 and CENPI expression led us to test the strength of CENPI overexpression as an independent marker for CIN in ER+ breast cancer." (PMID 28977935, 2017). "We compared CENPI mRNA expression levels in 2664 breast cancer samples to those in 269 normal control breast tissue samples using 22 previously published datasets." (PMID 28977935, 2017). "Together with our observation that CENPI overexpression is strongly associated with both aneuploidy and poor patient prognosis, this indicates that CENP-I overexpression promotes CIN during ER+ breast cancer development." (PMID 28977935, 2017). "Consistently, CENPI levels increase along with an increase in the number of chromosome arm gains or losses in ER+ breast cancer (p<0.05, t-tests; p<0.0001, F-test for trend line slope)." (PMID 28977935, 2017). "We next used the TCGA breast cancer RNAseq dataset to identify the genes that are most significantly co-expressed with CENPI in these cancers." (PMID 28977935, 2017). "We also assessed the prognostic strength of CENPI mRNA expression in ER+ and ER- breast cancers separately." (PMID 28977935, 2017). "Together, these data indicate that CENPI overexpression is a powerful independent marker for poor patient prognosis in ER+ breast cancer." (PMID 28977935, 2017). "Third, CENPI mRNA levels are increased in ER+ breast cancers, even when compensated for by the proliferation marker KI67 (p<0.0001, Mann Whitney U test)." (PMID 28977935, 2017). "This indicates that CENPI overexpression is a strong independent marker for chromosome instability in ER+ breast cancer." (PMID 28977935, 2017). "Using univariate Cox proportional hazard analysis on 3826 breast cancer samples, we demonstrated that CENPI overexpression is a strong marker for poor patient prognosis (p=6.13×10-10)." (PMID 28977935, 2017). "At the mRNA level, CENPI is overexpressed across all breast cancer subtypes." (PMID 28977935, 2017). "We further show that CENPI overexpression in breast cancer is also proliferation-independent." (PMID 28977935, 2017). "However, we also observed a significant increase in CENPI expression in male breast cancer and we find that even CENPI allelic copy number increases only modestly increase CENPI mRNA levels." (PMID 28977935, 2017). "Finally, we find that CENPI overexpression is a more powerful marker for CIN in ER+ breast cancers than most well established CIN markers." (PMID 28977935, 2017). "In addition, in ER+ breast carcinomas the degree of CENPI overexpression is proportional to the level of aneuploidy and CENPI overexpression is one of the strongest markers for CIN identified to date." (PMID 28977935, 2017). "Thus, these two tests independently indicate that CENPI overexpression is a strong independent marker for ER+ breast cancer patient prognosis." (PMID 28977935, 2017).
breast carcinoma (continued). "Interestingly, however, in this dataset lower CENPI levels conferred poorer distant metastasis-free survival for ER- breast cancers (p=0.0187, log-rank test)." (PMID 28977935, 2017). "Thus, CENPI overexpression causes CIN in vitro and strongly correlates with markers for both chromosome instability and aneuploidy in ER+ breast cancers." (PMID 28977935, 2017). "We find that CENPI overexpression is a marker for poor patient outcome in breast cancer." (PMID 28977935, 2017). "Next, we assessed whether CENPI allelic copy number gains or amplifications contributed to CENP-I overexpression using the TCGA breast cancer RNAseq and SNP6 array data." (PMID 28977935, 2017). "We find here that in ER+ breast cancer cells, CENPI overexpression also promotes CIN." (PMID 28977935, 2017). "Thus, while it is unclear whether CENPI levels are typically abnormal in breast cancer stromal cells, 20 out of 20 studies indicate that breast carcinoma intrinsic CENPI mRNA levels are significantly increased." (PMID 28977935, 2017). "Hormone receptor status strongly affects the prognostic strength of CENPI mRNA overexpression and CENP-I protein overexpression with their respectively being more powerful and higher in ER+ breast cancers." (PMID 28977935, 2017). "In fact, high CENPI expression consistently predicts poor prognosis in ER+ breast cancer patients, whereas high CENPI expression has either no prognostic power or forecasts better prognosis in ER- breast cancer patients." (PMID 28977935, 2017). "Consistent with our previous findings, the prognostic power of CENPI overexpression was highly significant for ER+ but not for ER- breast cancers." (PMID 28977935, 2017). "CENPI mRNA and protein levels are significantly elevated in estrogen receptor-positive (ER+) but not in estrogen receptor-negative (ER-) breast carcinoma." (PMID 28977935, 2017). "Our study shows that CENPI ranks in the 92nd percentile among these 70 well-established markers for CIN, indicating that CENPI overexpression is one of most powerful markers for CIN in ER+ breast cancer identified to date." (PMID 28977935, 2017). "Taken together, we conclude that elevated CENPI levels provide a significantly poor patient prognosis for ER+ breast cancers but not for ER- cancers." (PMID 28977935, 2017). "In addition, CENPI overexpression is a marker for poor prognosis for ER+ but not ER- breast cancer, even when multiple key clinical parameters included in Adjuvant!" (PMID 28977935, 2017). "Thus, while CENPI mRNA levels are elevated in breast carcinomas with CENPI copy number changes, this does not fully account for the observed CENPI overexpression." (PMID 28977935, 2017).
breast tumor (2 papers, 2017 to 2021). "We find that CENPI levels are significantly higher in aneuploid ER+ breast tumors than in diploid tumors (p<0.0001, t-test)." (PMID 28977935, 2017). "Moreover, in TCGA breast tumors, the predicted E2F1 transcription factor activity, inferred from the tumor sample’s protein expression profile using a trained affinity regression model, positively correlates with CENPI mRNA level in the tumors (r=0.5186, p<0.0001, Spearman correlation)." (PMID 28977935, 2017).
colorectal cancer (2 papers, 2020 to 2022). A primary or metastatic malignant neoplasm that affects the colon or rectum. "Upregulation of the CENPI gene that functions in cell proliferation typically confers poor prognosis in colorectal cancer." (PMID 35743743, 2022). "Another study showed similar link between overexpression of CENPI and colorectal cancer metastasis and progression." (PMID 33272232, 2020).
COVID-19 (1 paper, 2020). A disease caused by infection with severe acute respiratory syndrome coronavirus 2. "Mild-to-moderate expression of CENPI is seen in precursor B cells and late erythroid cells, but further studies are needed to ascertain the significance, if any, of CENPI expression, including in the context of COVID-19." (PMID 33024578, 2020).
diabetes (1 paper, 2025). "Additionally, we observed that CCNB2, XRCC2, and CENPI were elevated in BC tissues provided by patients with a diabetes history and associated with KI67 expression." (PMID 40202151, 2025).
ductal breast carcinomas (1 paper, 2017). "Data from seven independent studies show that CENPI mRNA levels are significantly higher in ductal breast carcinomas than in lobular breast carcinomas." (PMID 28977935, 2017). "In turn, medullary breast carcinomas show significantly elevated CENPI mRNA levels compared to ductal carcinomas." (PMID 28977935, 2017).
esophageal squamous cell carcinoma (1 paper, 2022). Esophageal squamous cell carcinoma (ESCC) is a type of esophageal carcinoma (EC) that can affect any part of the esophagus, but is usually located in the upper or middle third. "It has been reported that MCM4 and CENPI are involved in mediating chromosomal stability to influence the cell cycle and that KNTC1 knockdown suppresses cell viability and induces apoptosis in esophageal squamous cell carcinoma." (PMID 36035209, 2022).
Hyperglycemia (1 paper, 2025). An increased concentration of glucose in the blood. "Hyperglycemia treatment elevated the expression levels of CCNB2, XRCC2, and CENPI in BC cells, which correlated with increased cell proliferation and mobility." (PMID 40202151, 2025).
Infertility (1 paper, 2025). "Functional studies have shown that CENPI mutations disrupt centromere integrity, leading to meiotic inversion and, consequently, reproductive barriers and infertility." (PMID 39932629, 2025).
prostate carcinoma (1 paper, 2022). A carcinoma that arises from epithelial cells of the prostate gland. "MCM4, CENPI, and KNTC1 could serve as candidate diagnostic and prognostic biomarkers of castration-resistant prostate cancer and may provide potential preventive and therapeutic targets." (PMID 36035209, 2022).
tumor (10 papers, 2017 to 2026). "Therefore, elevated CENPI levels in nivolumab-responsive patients likely reflect expression in tumour-associated immune cells; indeed, proliferation is integral to an effective T cell immune response." (PMID 35743743, 2022). "In 21 of these, CENPI was significantly overexpressed in tumor samples compared to normal breast tissue." (PMID 28977935, 2017). "The K-M analysis revealed that CENPI overexpression in tumor patients indicates poor survival." (PMID 40406242, 2025). "Alternative hypotheses could be that CENPI-specific CD8+ T cells have been trapped or inactivated within the tumor, or that circulating precursor frequency among the used PBMC was too low to be detected and to allow amplification." (PMID 40008881, 2025). "In contrast, another study found that CENPI levels are increased in tumor stroma." (PMID 28977935, 2017). "Importantly, in the BALB/c mouse model, YTHDF3 overexpression-induced tumor progression could be partially abrogated by CENPI knockdown." (PMID 40406242, 2025). "Similar to other E2F target genes, as we and others have previously shown, we here find that CENPI overexpression promotes CIN, which facilitates tumor development and drug resistance in a variety of ways." (PMID 28977935, 2017). "The only dataset that showed significant CENPI underexpression compared tumor stroma – rather than tumor per se – to normal tissue." (PMID 28977935, 2017).
cancer (9 papers, 2017 to 2025). A tumor composed of atypical neoplastic, often pleomorphic cells that invade other tissues. "The pan-cancer analysis demonstrated that CENPI is a potential diagnostic and prognostic biomarker in various cancers including TNBC." (PMID 40406242, 2025). "CENPI mutations can be detected in some human cancers, such as adrenocortical carcinoma, lung adenocarcinoma, breast cancer, and colorectal cancer (CRC)." (PMID 40406242, 2025). "Of note, CENPI has previously been associated with cancer progression." (PMID 40008881, 2025). "Moreover, single-cell RNA sequencing analysis revealed that CCNB2, XRCC2, and CENPI are enriched in cancer cells within BC tissues." (PMID 40202151, 2025). "In addition, CENPI was related to immune cell infiltration and drug sensitivity in pan-cancer and can act as a potential treatment target to cure cancer patients." (PMID 40406242, 2025). "Like CENPF, CENPI is overexpressed in multiple cancers and deciphers worse prognosis." (PMID 37108172, 2023). "The rest 25 genes including CENPI, COMP and TROAP may be novel cancer-associated genes that are worthy of validation in further studies." (PMID 28489584, 2017). "However, compared to normal tissue, CENPI mRNA levels were significantly higher even in CENPI diploid cancers (p<0.0001)." (PMID 28977935, 2017). "Cancers displaying unfavorable risk with high ALT (BRCA, SARC, and LUAD) may be regulated by the transcriptional factors E2F4, TFDP1, E2F1, E2F7, and SIN3A (FDR = 0.001) in the DNA repair pathway, including genes repairing DNA damage such as CENPI, CLSPN, TOPBP1, and MCM4." (PMID 32784588, 2020). "CENPI is not part of the CIN70 gene expression signature for chromosome instability in human cancers." (PMID 28977935, 2017).
adenocarcinoma (1 paper, 2022). A common cancer characterized by the presence of malignant glandular cells. "Finally, we investigated whether the expression of MCM4, CENPI, and KNTC1 was associated with the NEPC score, which was introduced to quantify the degree of CRPC-adenocarcinoma (CRPC-Adeno) conversion to CRPC-neuroendocrine (CRPC-NE), a more aggressive variant of CRPC." (PMID 36035209, 2022).
CENPI also shares sentences with these, for which no sentence is quoted: glioma (2 papers); autoimmune disease (1); colon cancer (1); glioblastoma (1); hepatocellular carcinoma (1); infection (1); lobular breast carcinomas (1); lung carcinoma (1); male breast carcinoma (1); medullary breast carcinoma (1); small cell lung carcinoma (1); systemic sclerosis (1).